RAC1 (Rac family small GTPase 1)
Diseases named in the same sentence as RAC1 in open-access papers (continued):
Sharing a sentence is not in itself a finding about the gene and the disease.
Hypertension (continued). "Summing up the results of existing studies, we can learn that several proteins are involved in regulating the progression of high blood pressure, such as endothelin-1, Rac1, and G protein-coupled estrogen receptor, but hypertension-related genes have not been identified systemically." (PMID 33621262, 2021). "We also investigated the cross talk between AMPK and Rac1 in the pathogenesis of hypertension." (PMID 27138844, 2016). "The aim of this study was to examine whether the activation of AMPK in the brain decreased Rac1-induced ROS generation, thereby reducing blood pressure (BP) in rats with fructose-induced hypertension." (PMID 27138844, 2016). "Furthermore, it is unclear whether AT1R/PKCγ/Rac1/NAD(P)H pathway in PVN mediates ROS production in the development of hypertension." (PMID 28338001, 2017). "However, the effects of AMPK and Rac1-induced ROS in the brain on the regulation of fructose-induced hypertension in vivo are unknown." (PMID 27138844, 2016). "To investigate whether resveratrol limits ROS production via inhibiting Rac1 activation of NADPH oxidases during fructose-induced hypertension, we examined the activity and expression of Rac1, NADPH oxidase subunits and SOD when both fructose and resveratrol were administered." (PMID 27138844, 2016). "In addition, since Rac1 GTPase and mineral corticoid receptors are activated in salt-induced hypertension, the mental distress patient with hypertension and lower daily salt intake might have a lower activity of Rac1 GTPase and mineral corticoid receptors." (PMID 26109460, 2015). "Because PKC γ/Rac1/NAD(P)H is a close signal pathway regarding oxidative stress in the PVN in salt-induced hypertension, the high salt diet increases the expression of NKA α2, PKC γ, and p-Rac1 in the PVN compared to vehicle." (PMID 35204171, 2022). "To determine the effects of IBAN during the progression of hypertension in SHR, we conducted western blotting to detect the change of Rac1-mTOR-autophagy." (PMID 35397636, 2022). "In Wistar rats, high salt intake induced hypertension, increased levels of AT1R, PKCγ, and Rac1 activity and superoxides, but decreased the levels of antioxidants in the PVN compared to those in the control animals." (PMID 33803946, 2021). "PVN infusion of LOS not only attenuated the PVN levels of AT1R, PKCγ, Rac1 activity, superoxide and decreased the arterial pressure, but also increased the PVN antioxidant capacity in hypertension." (PMID 28338001, 2017). "We demonstrated the importance of the activation of AMPK abolished the Rac1-modulated increase in NADPH oxidase activity and decreases in SOD2 activities in the RVLM during fructose-induced hypertension." (PMID 27138844, 2016). "Furthermore, the AT1R pathway is responsible for promoting hypertension, G protein-dependent signaling, transactivation of growth factor receptors, NADPH oxidase, and ROS signaling explaining why the RAC1 gene was enriched by the AT1R pathway." (PMID 34805976, 2021). "Inhibition of Nox1 and its regulator Rac1/2 with ML171 and EHT1864 respectively, restored hypercontractility suggesting a functional link between Nox1 upregulation and impaired vascular function in hypertension." (PMID 28478264, 2017). "We hypothesized that the promotion of AMPK decreased Rac1-induced ROS generation, increased NOS and reduced BP during fructose-induced hypertension." (PMID 27138844, 2016). "Despite the role of the Ald/MR pathway in the distal nephron and the non-MR Rac1-mediated pathway in the pathogenesis of hypertension and hypokalemia being well-established, the function of MR and Ald-mediated electrolyte transport in the PTs remains unclear." (PMID 41458378, 2025). "In contrast, mice with smooth muscle‐specific Rac1 knockout developed hypertension as well, due to increased vascular resistance but not due to changes in diastolic blood pressure or heart rate, by disruption of nitric oxide‐induced relaxation in vascular smooth muscle cells." (PMID 41252219, 2025).
Hypertension (continued). "However, further in-depth studies are needed to determine the direct evidence of NKA α2 regulation of their downstream pathways that regulates Rac1-dependent oxidative stress and TLR4-induced inflammation in the PVN during the development of high salt-induced hypertension." (PMID 35204171, 2022). "However, hypertension and renal injury induced by Rac1-GEF, Rac1, and sequential MR activation could not be observed in high-salt-fed Dahl salt-resistant (DR) rats, salt-fed adrenalectomized DS rats, and low-salt-fed DS rats." (PMID 33803946, 2021).
viral infection (28 papers, 2010 to 2025). "The activation of Rac1 has also been implicated in virus infection." (PMID 30131810, 2018). "Rac family (exemplified by Rac1): Constructing branched actin networks in the context of viral infection." (PMID 41332982, 2025). "Rac1-mediated activation of formins is specific to contexts of viral infection (e.g., vaccinia virus infection)." (PMID 41332982, 2025). "Ras-related C3 botulinum toxin substrate 1 (Rac1), which is a member of the Rho family of small GTPases, plays an important role in various cellular signaling pathways and regulates many viral infections." (PMID 39931518, 2024). "In contrast, inactive Rac1 impeded the viral infection level compared with the effect of Rac1 WT, which was consistent with the outcome of NSC23766 treatment." (PMID 38809020, 2024). "Our results demonstrate that Rho GTPase activity facilitates viral infection, and inhibition of the Rho GTPase, Rac1, is detrimental to the replicative cycle of RSV." (PMID 34716403, 2021). "Localization of Rac1 to the plasma membrane is dependent on post-translational prenylation of the protein, a process which we found to be promoted by viral infection and blocked by statins." (PMID 34716403, 2021). "Members of Rho family small GTPases, such as Rac1 and Cdc42, were described to play roles in virus infection." (PMID 32645930, 2020). "First, time-of-addition experiments with Rac1 and Arp3 inhibitors demonstrated that both factors function at a late stage of virus infection." (PMID 27031835, 2016). "The use of a RhoA, B and C inhibitor, as well as a Rac1 inhibitor, reduced virus infection." (PMID 40167026, 2025). "In invertebrates, Rac1, a member of the Rho GTPase family, was highly expressed in the hemocytes of the Chinese shrimp Fenneropenaeus chinensis, and the expression was upregulated following viral infection." (PMID 38274813, 2023). "However, viral infection leads to geranylgeranylation and palmitoylation of Rac1, which inhibits the TRIM31–MAVS interaction and suppresses innate immunity; interestingly, under physiological conditions, Rac1 can also inhibit MAVS aggregation." (PMID 32536927, 2020). "The role of of Rac1 or local ionic conditions in promoting viral infection remains to be studied." (PMID 26690201, 2015). "The AAV encoding Rac1-DN/EGFP or control EGFP was bilaterally infused into BLA of C57BL/6 mice and the expression of EGFP reporter in BLA could be detected 2 weeks after viral infection." (PMID 26582975, 2015). "For other flaviviruses, it was shown that the expression of the dominant-negative GTPase mutants of Rac1 and Cdc42 in HMEC-1 cells specifically inhibits the formation of filopodia induced by DENV-2 leading to a reduction in viral infection and titer." (PMID 34834920, 2021). "Rac1 can be activated by a variety of stimuli, including growth factors (such as EGF and PDGF) and virus infection (HBV)." (PMID 24274578, 2013). "Rac1 inhibitor strongly decreases the ASFV-induced ruffles, in accordance with the decrease in virus uptake, viral infection (6G) and virus production (6H) previously observed." (PMID 22719252, 2012). "Rho GTPases, including Rac1 in the context of DENV infection, have been suggested to promote viral entry via actin interactions, and thus, there is a precedence for manipulation of Vav-Rac-Rho signaling to impact on early viral infection." (PMID 38054722, 2024). "These include DOCK2, which is known to activate RAC1/RAC2 genes required for implantation, and TRIM25, a gene involved in innate immune response against viral infection, mediating estrogen action and whose downregulation during embryogenesis in medaka has been shown to result in apoptosis." (PMID 37789509, 2023). "We also show that inhibitors of Rac1 and Cdc42 did not block virus entry, but inhibited overall virus infection." (PMID 32645930, 2020). "Inhibitors of the EGFR pathway and the effectors Pak1, Rac1 and PKC reduced viral infection." (PMID 28596575, 2017).
viral infection (continued). "Our previous results demonstrated that NS1 over-expression and wt virus infection resulted in a reduced level of GTP-bound Rac1, next we investigated whether NS1 regulates Rac1 activity through a direct interaction." (PMID 27869202, 2016). "The results suggested that non-enveloped HEV may indirectly trigger the RAC1 signaling pathway being involved in the viral infection as observed for other viruses." (PMID 34790187, 2021). "Thus, we analyzed the effect of inhibiting Rho, Rac1, and ROCK kinases on virus infection." (PMID 29970183, 2018). "In addition, our results are aligned with a recent study demonstrating that the N-terminal fragment of the Slit2 protein inhibits X4 and R5 viral infection by binding to the Robo1 receptor and antagonizing the HIV gp120-mediated Rac1-LIMK-cofilin pathway for actin rearrangement." (PMID 23782904, 2013). "Inactive Rac1 suppressed viral infection, which was validated by NSC23766 treatment and negative-dominant Rac1 transfection." (PMID 38809020, 2024).
breast tumors (26 papers, 2002 to 2025). "RhoA, RhoB, Rac1/Rac1b, and Cdc42 are overexpressed in breast tumors, with RhoA expression associated with advanced stages of the disease." (PMID 19703301, 2009). "With respect to rac1 a splice variant named rac1b was recently cloned both from colorectal and breast tumours." (PMID 12237774, 2002). "The combined quantitative assessment of RAC1B and RAC1 in tumor biopsies of BC patients may represent a novel diagnostic tool for probing molecular subtype and eventually predict malignant potential of breast tumors." (PMID 33567745, 2021). "We then used a meta dataset of 2999 primary breast tumours to explore whether RAC1 expression associated with particular subtypes of breast tumours." (PMID 22689141, 2012). "Sodium channel 1.5(NaV1.5) and the GTPase Rac1 are factors related to the degree of malignancy of breast tumors." (PMID 39673684, 2025). "Rac1, a GTP binding protein, also triggered DNA damage repair by increased nucleotides metabolism to support neoadjuvant chemotherapy (NAC) resistant breast tumors, while silencing Rac1 expression by nanoparticles resensitized the cancer cells." (PMID 35646898, 2022). "Together, these results suggested that silencing Rac1 enhanced the chemosensitivity of breast tumors." (PMID 32193458, 2020). "RhoA, Rac1, and Cdc42 are overexpressed in human breast tumors and are all essential for cell migration, indicating that the migratory phenotype we observed in Cx43-shRNA S1 cells is triggered downstream of Rho GTPase signaling." (PMID 30857262, 2019). "The small GTPase Rac1 potently activates cell motility in breast tumor cells, and is required in normal mammary epithelial cells downstream of mTORC2." (PMID 28666462, 2017). "The initial evidence for Rho GTPases in breast tumor invasion and metastasis in vivo came from studies expressing dominant negative forms of RhoA, RAC1 and Cdc42." (PMID 27902969, 2017). "Research showed ankyrin-Tiam1 interaction plays a pivotal role in regulating Rac1 signaling and cytoskeleton function required for oncogenic signaling and metastatic breast tumor cell progression." (PMID 28245581, 2017). "Breast tumor cells from patients with recurrent disease had RAC1 expression localized at the plasma membrane, suggesting activation of RAC1, in patients with aggressive BC." (PMID 27902969, 2017). "Here, using an insertional mutagenesis screen in mammary epithelial cells that express wild-type neu, we identify and establish HACE1 as a breast tumor suppressor gene that attenuates the levels of activated Rac1." (PMID 25659579, 2015). "Rac1 is overexpressed or hyperactive in breast tumors and Rac1-GEFs are overexpressed in high-grade poor-prognosis breast tumors." (PMID 25799492, 2015). "Rac1+ epithelial cells in breast tumours also contain high levels of the phosphorylated form of the transcription factor STAT3." (PMID 22689141, 2012). "In addition, a high-throughput functional screen using interference RNA to target genes commonly amplified in breast tumors with acquired resistance identified RAC1 as one of the most relevant proteins involved in the mechanisms of resistance." (PMID 40633540, 2025). "We developed an endosomal pH-responsive nanoparticle to carry the Rac1 siRNAs together with cisplatin, which resulted in an effective delivery of the Rac1 targeting oligonucleotide and cisplatin in breast tumors and exhibited a promising synergetic anti-tumor effect." (PMID 32193458, 2020). "With regard to the specific targets predicted to TNBC, TIAM1 encodes Tiam1 (T-lymphoma invasion and metastasis 1), one of the known guanine nucleotide (GDP/GTP) exchange factors (GEFs) for Rho GTPases (e.g., Rac1) and is expressed in breast tumor cells (e.g., SP-1 cell line)." (PMID 28245581, 2017). "RAC1 was found to be significantly higher expressed in breast tumours than in normal breast tissue." (PMID 22689141, 2012).
breast tumors (continued). "We propose that in these breast tumour cells this reciprocal antagonism between RhoA and Rac1 precisely coordinates the specificity and/or magnitude of the pathophysiological response of NHE1 to serum deprivation, with concomitant increases in motility and invasion and hence malignant progression." (PMID 15535843, 2004). "Our results demonstrated an inverse correlation of RAC1 and RAC1B expression in terms of the ER, PR, or HER2 status of breast tumors." (PMID 36599922, 2023). "By analyzing mRNA expression profile, we identify that Rac1, a small GTP binding protein, is overexpressed in chemoresistant breast tumor tissues and cell lines." (PMID 32193458, 2020). "We examined Rac1 and phospho-Ser727 STAT3 levels by antibody staining in human breast tumours (n=6)." (PMID 22689141, 2012). "Then, we evaluated whether the siRac1/DDP NPs could silence Rac1 expression and recovered the chemosensitivity of NAC resistant breast tumors in the PDX model." (PMID 32193458, 2020). "Here, we demonstrate that RAC1 SUMOylation is important for optimal breast tumour cell migration and invasion but not for other RAC1 functions, such as proliferation and survival." (PMID 31578236, 2019). "Similarly the alterations of RAC1 gene are the highest in PAM50 Basal tumors (40%), ER-ve breast tumors (57%) as well as PAM50 Basal tumors (60%), as compared to other BC subtypes." (PMID 27902969, 2017). "At variance with other solid tumors, in which the malignancy-associated role of Vav1 has been variously linked to its GEF activity, opposite effects for Vav1 on Rac1 activation were reported in AU565 and MCF7 breast tumor-derived cell lines, also in the presence of cytoskeleton changes." (PMID 24962430, 2014). "Moreover, in vitro assays indicate that inhibition of ICMT-mediated methylation results in decreased motility of breast tumor cells by reducing the GTP-bound RhoA and Rac1." (PMID 25361001, 2014). "The data show at the first time that the amount of RhoA-like proteins but not of Rac1 and Cdc42, is related to clinically established prognostic breast tumour markers such as histological grade and proliferation index." (PMID 12237774, 2002). "For breast tumours we found that there was only a tendency in the expression of rhoB, rhoC and rac1 mRNA, but not of rhoA mRNA, to increase with grading." (PMID 12237774, 2002).
bladder cancer (24 papers, 2013 to 2025). "Numerous studies have reported alterations of Rac1 expression and function in bladder cancer, and the expressed protein has been associated with a variety of functional alterations." (PMID 35740379, 2022). "On the one hand, high levels of NRBP1 have been shown to enhance proliferation and metastasis in bladder cancer, as well as influence the oncogenic potential of triple-negative breast cancer cells via the P-Rex1/Rac1/Cdc42 pathway." (PMID 41430038, 2025). "For example, SHCBP1 enhances the migration and invasion of bladder cancer cells by inhibiting RACGAP1-mediated Rac1 inactivation." (PMID 40799237, 2025). "We demonstrated that hAM homogenate significantly decreased the expression of Cdc42 and Rac1/2/3 in bladder cancer urothelial T24 and RT4 cells." (PMID 37932474, 2023). "A recent study has shown that the adaptor protein RacGAP1 inactivated GTP-bound Rac1 in bladder cancer, but the activation was inhibited by protein SHCBP1 (SHC-binding protein 1), which is a regulator of EGF (epidermal growth factor)." (PMID 35740379, 2022). "The findings above suggest that the movement of bladder cancer cells is at least partially dependent on the activity of RAC1." (PMID 35013128, 2022). "To date, however, nothing is known about the role of Rac1 in bladder cancer stemness and invasion or about the functional relationship linking Rac1 with SNHG1." (PMID 36077697, 2022). "In summary, our research has identified SHCBP1 as a new mediator of the crosstalk between EGF/EGFR signaling and RAC1 and a new mechanism mediating the progression of bladder cancer." (PMID 35013128, 2022). "The short 3’UTR isoform of Rac1 apparently plays an essential oncogenic role in the pathogenesis of bladder cancer." (PMID 35740379, 2022). "The Rac1 protein is one of the elements that contributes to the proliferation and dissemination of bladder cancer cells." (PMID 35740379, 2022). "Specifically, we found that the increased Rac1 protein in bladder cancer cells over-expressing SNHG1 was due to the increased stability of Rac1 mRNA, and that this was associated with low levels of miR-129-5p." (PMID 36077697, 2022). "Rac1 plays a role in the carcinogenesis of various cancers, including bladder cancer but also hepatocarcinoma, breast cancer, non-small-cell-lung cancers and others." (PMID 35740379, 2022). "For these reasons, we will not discuss further these aspects here, but they provide additional indirect lines of evidence supporting the interest of targeting activated Rac1 in bladder cancer." (PMID 35740379, 2022). "Here, we show that SNHG1, a long non-coding RNA that is over-expressed in ~95% of human muscle-invasive bladder cancers (MIBCs), induces stem-cell-like sphere formation and the invasion of cultured bladder cancer cells by upregulating Rho GTPase, Rac1." (PMID 36077697, 2022). "Altogether, we clearly show that SNHG1 over-expression inhibits miR-129-5p expression, thereby reducing the ability of the latter to bind to the 3′-UTR Rac1 mRNA and increasing the stability of Rac1 mRNA and promoting bladder cancer cell stemness and invasion." (PMID 36077697, 2022).